KEAP1 (kelch like ECH associated protein 1)
Diseases named in the same sentence as KEAP1 in open-access papers (continued):
Sharing a sentence is not in itself a finding about the gene and the disease.
cancer (715 papers, 2010 to 2026). A tumor composed of atypical neoplastic, often pleomorphic cells that invade other tissues. "In cancer, however, its sustained activation, often linked to loss-of-function mutations in Keap1, confers resistance to ferroptosis and facilitates tumor progression." (PMID 41415550, 2025). "Specific somatic mutations in KEAP1 or NRF2 that lead to the constitutive activation of the NRF2 pathway have been identified in a variety of cancer types, including lung, head and neck, and esophageal cancers." (PMID 39941813, 2025). "Our findings demonstrate that melatonin potentiates gemcitabine’s cancer-suppressing effects via modulation of the Kelch-like-ECH associated protein-1 (Keap1)/p62 pathway, resulting in reduced fibrosis, oxidative stress, and inflammatory markers." (PMID 40100373, 2025). "Through the ETGE and DLG motifs, two conserved motifs found in Nrf2′s N-terminal tail, Keap1 interacts with Nrf2 and these motifs have been identified to contain somatic mutations of Nrf2 in cancer." (PMID 40422216, 2025). "Tumor growth was greatly decreased across all three cancer mutation statuses (WT, KEAP1 KO, and NRF2 KO)." (PMID 41462606, 2025). "This has been proposed to be highly relevant to cancer biology, as cancer therapy is often associated with impairments in Keap1-dependent regulation of Nrf2." (PMID 40315422, 2025). "Further analysis revealed that proteins carried by the nanoparticles included various neoantigens derived from mutations recorded in the Catalog of Somatic Mutations in Cancer, such as PlOD2, KEAP1, and PIH1D1." (PMID 39498880, 2025). "Somatic mutations in KEAP1 in cancer tissues and cancer-derived cell lines are advantageous for cell growth." (PMID 39373520, 2025). "The identification of Nrf2-Keap1 mutations in cancer has led to interest in developing targeted therapeutic strategies, such as small molecule inhibitors of Nrf2 or Keap1." (PMID 40422216, 2025). "For example, the inappropriate activation of NRF2 associated with KEAP1 loss-of-function mutation is an important oncogenic event in many human cancers." (PMID 40075648, 2025). "ML385 exerted highly selective cytotoxicity to cancer cells with KEAP1 mutations and showed significant anti-cancer efficacy when combined with carboplatin treatment in NSCLC." (PMID 40847302, 2025). "For instance, KEAP1, a negative regulator of the Nrf2 signaling pathway, plays a pivotal role in cellular antioxidant responses and is associated with various types of cancer." (PMID 40228435, 2025). "Loss-of-function KEAP1 mutations in cancer cells contribute to NRF2 activation and tumor immune evasion through immunosuppression and drug resistance." (PMID 41462606, 2025). "The hyperactivation of Nrf2 through mutations in both Keap1 and Nrf2 has been observed in various cancers, such as ovarian cancer and pulmonary papillary adenocarcinoma." (PMID 40722961, 2025). "Under physiological conditions, this pathway protects cells from oxidative damage, however, sustained activation of NRF2 in cancer, often due to mutations in KEAP1, supports tumor cell survival, drug resistance, and metabolic reprogramming." (PMID 40746900, 2025). "During the oxidative stress associated with ferroptosis, cancer cells activate p62, which in turn stimulates the autophagic degradation of KEAP1." (PMID 39846413, 2025). "Independently of KEAP1/NRF2/CUL3 mutations, altered protein-protein interactions and KEAP1-inactivating posttranslational modifications also activate NRF2 in cancer, most notably in tissues of the liver, breast and kidney." (PMID 40027760, 2025). "Knockdown of Keap1 reduces cyclin D1 and cancer stem cell markers, whereas it enhances PPARγ in chemotherapeutic agent arsenic trioxide-administered A549 cells, suggesting that Keap1 modulation is associated with the regulation of chemosensitivity." (PMID 40722961, 2025).
cancer (continued). "Genetic alterations are a major driver of NRF2 dysregulation in cancer, particularly mutations in KEAP1, NFE2L2 (NRF2), and CUL3, which disrupt KEAP1-mediated ubiquitination and lead to constitutive NRF2 stabilization." (PMID 41470226, 2025). "ML385 has also been shown to have the ability to resensitize chemoresistant tumors to platinum-based therapies, suggesting a therapeutic synergy in KEAP1-deficient cancers." (PMID 41470226, 2025). "The occurrence of the genetic mutations in Nrf2 is documented concerning Loss-of-function (LOF) somatic mutation in the KEAP1 gene, elevating levels of transcription activity in tumor cells, presenting survival benefits to the cancer cells." (PMID 41154495, 2025). "In some critical diseases (e.g., cancer), Keap1 has also been found to be somatically mutated, resulting in deregulation of its function in mediating ubiquitination, leading to cancer initiation and malignant progression." (PMID 38634043, 2024). "KEAP1 mutations have been observed in various cancers, with NSCLC exhibiting the highest mutation frequency up to 15%." (PMID 38521813, 2024). "Mutations within the Keap1/Nrf2 signaling pathway have been implicated in the development of resistance to cancer chemotherapy, targeted therapies, and radiotherapy." (PMID 39872524, 2024). "Nrf2 overexpression starts out playing a protective role in cancer, but ultimately encourages disease progression and metastasis, while mutations in Keap1 have been linked to a poor prognosis in individuals with advanced NSCLC receiving treatment." (PMID 39557840, 2024). "In cancer, Nrf2 unbinds from Keap1, enters the nucleus, and causes activation of transcription factors, resulting in drug resistance, enhanced cell proliferation, stress adaptation, and activation of metabolic reprogramming." (PMID 38336617, 2024). "The accumulation of Nrf2 within cancer cells, along with its cytoprotective effects, can be attributed to somatic mutations in Nrf2, Keap1, or CUL3." (PMID 39872524, 2024). "Comprehensive genomic analyses have identified somatic mutations and other alterations in the KEAP1 or NRF2 genes in various types of cancer, and Nrf2 mutations occur less frequently than Keap1 mutations." (PMID 38241355, 2024). "Research focused on NSCLC with KRAS driver mutations, in particular, the KRAS p.G12C mutation, shows that co-mutations in STK11 and/or KEAP1 make these cancers notably resistant to standard therapies, including targeted and immune-based treatments." (PMID 39001451, 2024). "This study sought to identify changes in the immune microenvironment caused by cancer-specific KEAP1 mutations." (PMID 38542481, 2024). "Cancers harbouring Kelch-like ECH-associated protein 1 (KEAP1) mutations show enhanced NRF2-dependent antioxidant defence but become dependent on the uptake of several NEAA, including serine." (PMID 38698089, 2024). "Cancer genome sequencing studies have identified that KEAP1 is mutated in approximately 20% of both adenocarcinoma and squamous lung cancers." (PMID 38413563, 2024). "We sought to characterize immune microenvironmental alterations caused by cancer cell-intrinsic KEAP1 mutations while preserving the NRF2 status of immune cells." (PMID 38542481, 2024). "Overall, our data suggest that some ARID1A-deficient cells maintain elevated levels of KEAP1, perhaps as a mechanism to sustain the growth of these cancer cells." (PMID 39272807, 2024). "Cellular redox-state regulating enzymes such as nuclear factor erythroid 2-related factor 2 (Nrf2), Kelch-like ECH-associated protein 1 (Keap1), and manganese superoxide dismutase (MnSOD) have been studied in various cancer types." (PMID 39040459, 2024).
cancer (continued). "Research indicates that mutations in the Keap1/Nrf2 pathway or imbalanced regulation of this system contribute to the development of tumors in people and facilitate the advancement of cancer by continuously activating Nrf2 and altering cell metabolism." (PMID 39286246, 2024). "To determine how KEAP1 mutations impacted the intrinsic phenotype of the cancer lines and how they are implicated in immunosuppression, we used a multiplex assay to evaluate the secretome of the KO lines." (PMID 38542481, 2024). "Despite these intriguing findings in the immune system, there is a paucity of studies relating NRF2 activation and anti-inflammatory activity in cancer cells, which is important since cancers with KEAP1 mutations are resistant to immune checkpoint inhibition." (PMID 38542481, 2024). "The NRF2 protein is activated by tumor suppressor gene products such as breast cancer susceptibility gene I and p21Cip1 by inhibiting KEAP1/NRF2 complex formation in microenvironmental cells in tumors." (PMID 39404411, 2024). "The authors demonstrated the prognostic significance of KEAP1 mutations in both early-stage (p = 0.0099) and advanced-stage cancers (p < 0.0001)." (PMID 39273605, 2024). "Nclear factor (erythroid-derived 2)-like 2 (NRF2) and its negative regulator, KEAP1 are frequently mutated in cancer, these mutations drive constitutive NRF2 activation and correlate with poor prognosis." (PMID 38962454, 2024). "Since KEAP1 and ARID1A are commonly mutated in cancer, we compared mRNA expression of KEAP1 and ARID1A in a large cohort of solid tumors of various origins from The Cancer Genome Atlas (TCGA) datasets." (PMID 39272807, 2024). "It has also been implicated that the Nrf2/Keap1/ARE signaling cascade is associated with metabolic reprogramming in cancer cells via modulating multiple mechanisms." (PMID 39407193, 2024). "The Keap1-Nrf2 signaling pathway can prevent organ and cell damage caused by oxidative stress and protects against the occurrence and development of cancer." (PMID 38634043, 2024). "We found a cancer cell-intrinsic immunosuppressive phenotype directly caused by the loss of KEAP1 that was associated with increased recruitment and polarization of M2-like macrophages." (PMID 38542481, 2024). "Frequent inactivation or mutation of KEAP1 is observed in human cancers, and KEAP1-mutant tumors are frequently resistant to conventional therapies." (PMID 37371948, 2023). "It is very likely that we tackled an Nrf2 decay pathway that functions in cells that are depleted from KEAP1 and deprived of GSK3beta activity (as, e.g., possibly found in cancers with KEAP1 mutation and overactive PI3K signaling)." (PMID 37627580, 2023). "Somatic mutations in the KEAP1 or NRF2 gene in cancer cells as well as other mutations that disrupt the binding of KEAP1 to NRF2 lead to aberrant NRF2 activation." (PMID 36830722, 2023). "In cancer cells, Nrf2 can be activated by mutations or the epigenetic silencing of Keap1 as well as by the transcriptional activation via oncogenes like k-ras, c-myc, or b-raf." (PMID 38201509, 2023). "Consistent with the cell line data, a significant increase in FSP1 abundance was observed in individuals with KEAP1 mutations across both the pan-cancer and LUAD cohorts." (PMID 37633973, 2023). "Mutations of Nrf2 or its repressor Keap1 are also found in cancer cells, resulting in Nrf2 overactivation and promoting cancer cell survival." (PMID 37371607, 2023). "For Keap1, methylation mostly happens on its promoter and is often closely associated with cancer, such as colorectal cancer, renal cancer, and triple-negative breast cancer (TNBC)." (PMID 38259518, 2023). "They experimentally determined that fumarate accumulation due to FH deficiency causes succinylation of Keap1 and that the pathophysiological levels of fumarate associated with cancer are sufficient to make Keap1 succinylation and activate Nrf2 signaling." (PMID 38259518, 2023).
cancer (continued). "MLN385 exerts inhibitory activity on KEAP1-mutated non-small-cell lung cancer cells and is a candidate drug for the treatment of cancers with NRF2 activation, including ESCC." (PMID 36661697, 2023). "Several natural products, like curcumin and lycopene, can disrupt Keap1 and activate Nrf2 during the process of causing cancer cell death." (PMID 38086844, 2023). "In cancer, genetic alterations in KEAP1 or NFE2L2 (encoding NRF2) are the most common cause of NRF2 hyperactivation." (PMID 36632216, 2023). "Under oxidative stress, NRF2 dissociates from the KEAP1-Cullin3 complex and translocates to the nucleus, where it activates the expression of cytoprotective genes implicated in protection against cancer." (PMID 37511619, 2023). "Among the 16,616 genes with mutations in various cancers, we found that KEAP1 mutations were the most significantly enriched in NSCLC cell lines that exhibited resistance to FINs (Fisher’s exact test, p < 1e-04)." (PMID 37633973, 2023). "This review provides a comprehensive summary of the clinical efficacies of current therapeutic strategies against NSCLC harboring LKB1 and/or KEAP1 mutations, along with the metabolic alterations in glycolysis and glutaminolysis observed in these cancer cells." (PMID 37675220, 2023). "The activation of Keap1 leads to intracellular iron accumulation which causes ferroptosis in cancer cells." (PMID 36597133, 2023). "According to these findings, a defect in the function of Keap1-Cul3 causes a significant rise in the chemical resistance of cancer cells due to the resulting increase in Nrf2." (PMID 37841775, 2023). "These genes included Kelch ECH associating protein 1 (KEAP1), a sensor of oxidative stress, which has been confirmed to contribute to the progression and resistance to chemo- and radiotherapy in many types of cancers." (PMID 37251921, 2023). "NSCLC with STK11 and/or KEAP1 mutations represents one of most aggressive types of cancer, characterized by resistance to standard cytotoxic chemotherapy or radiotherapy." (PMID 37675220, 2023). "KEAP1 mutations are present in various pathological conditions, including neurological and metabolic disorders, cardiovascular diseases, and cancer, with a high prevalence in lung and pancreatic cancer." (PMID 37627580, 2023). "Activation of Nrf2, which is equal to the inhibition of Keap1, can be a pharmacological target in certain diseases linked with oxidative stress and inflammation, such as cancer, as well as metabolic, vascular, and neurodegenerative diseases." (PMID 36902097, 2023). "Functional loss of Keap1 results in significant activation of Nrf2 and promotes cancer cell growth, proliferation, and elevated cancer stem cell (CSCs) self-renewal efficiency and resistance to oxidative stress." (PMID 35945195, 2022). "To explore the underlying mechanisms leading to the dysregulation of KEAP1 in cancer, we first characterized genomic alterations of the KEAP1 gene." (PMID 35453346, 2022). "Given that the role of Keap1-Nrf2 signaling in cancers is more commonly investigated by using loss-of-function mutants of KEAP1, the role of its wildtype protein in regulating tumor cell behavior remains largely unexplored." (PMID 36321803, 2022). "The KEAP1-NFE2L2 pathway is frequently perturbed in cancer with inactivating mutations in KEAP1 or activating mutations in NFE2L2 reported in more than 30% of lung squamous tumors." (PMID 35382456, 2022). "Loss of Keap1 has been identified as a possible mechanism of chemoradiation resistance in many cancers." (PMID 35945195, 2022). "The inactivation of KEAP1 promotes cancer growth and metastasis and is associated with resistance to not only cytotoxic anticancer agents and radiotherapy but also ICIs because the inactivation of the KEAP1 gene results in immunologically cold tumors." (PMID 36614938, 2022).
cancer (continued). "Of note, copy number alterations (especially deep deletion or arm-level deletions) of KEAP1 at 19p13 were associated with substantially lower immune infiltrates in most cancer types NSCLC." (PMID 36136862, 2022). "Mutations, copy number changes, and structural variants for KEAP1 were analyzed across human cancers using the cBioPortal database." (PMID 35453346, 2022). "The Keap1-Nrf2 pathway has been shown to cancer cell survival and mutations in Keap1 or Nrf2 are clinically relevant predictive biomarkers of chemo-radio resistance." (PMID 35945195, 2022). "Our observation from this study suggests a pivotal role for Keap1 mutations during HNSCC oncogenesis due to the deletion of Keap1 led to the increased self-renewal activity of cancer cells and subsequent therapeutic resistance." (PMID 35945195, 2022). "Together, our study proposes that KEAP1-NRF2 controls both the SLC7A11-GSH-GPX4 and CoQ-FSP1 arms for ferroptosis defense; consequently, if one arm is disabled, KEAP1 deficient cancer cells can still utilize the other arm to defend against ferroptosis." (PMID 35459868, 2022). "For example, SLIdR identified NFE2L2 as the SL partner of the mutated KEAP1, both of which play an important role in cancer through Nrf2 pathway activation." (PMID 36517508, 2022). "Constitutive activation of Nrf2 by inactivating mutations in KEAP1 or activating mutations in Nrf2 interferes with the KEAP1-Nrf2 interaction, reprogramming glucose metabolism to support cell proliferation and contribute to cancer progression." (PMID 35453346, 2022). "While cancers frequently harbor loss-of-function mutations in KEAP1 and CUL3 or gain-of-function mutations in NFE2L2 (encoding NRF2) itself, no such mutations have been detected in uterine leiomyomas." (PMID 36068196, 2022). "Due to this direct interaction, Keap1 has been identified as a master inhibitor of Nrf2, with its high- or low-expression levels in the human lung, breast, liver, and other somatic cancers, hence, causing changes in endogenous Nrf2 abundances." (PMID 36142252, 2022). "Loss of Keap1 and Nrf2 overexpression induces many stress resistance genes and can restore cancer cell proliferation." (PMID 35945195, 2022). "Mutation frequencies vary greatly across different cancer types, but interestingly, some cancers show high rates of Nrf2 pathway alterations but low rates of KEAP1 or NFE2L2 mutations." (PMID 36552553, 2022). "MiRNA, the most common and effective ncRNA, has been substantiated to epigenetically regulate NRF2/KEAP1 signaling, considered as a hallmark of cancer." (PMID 35754474, 2022). "It is widely accepted that the Keap1-Nrf2 signaling pathway is associated with the proliferation of cancer cells and tumorigenesis through metabolic reprogramming." (PMID 35534896, 2022). "The KEAP1/NFE2L2 mutational status has been directly linked to the responsiveness of certain cancer types to radio- and chemotherapy." (PMID 35163828, 2022). "Determining if activation of Nrf2 causes cancer, how to target Nrf2 (direct or indirect suppression of upstream protein kinases), and elucidating the structure of Keap1 have therefore been the focus of academic research." (PMID 35993016, 2022). "In concordance with these previous results, our results demonstrated that downregulation of the Nrf2 expression in Keap1 mutated cancer cells or introduction of Keap1 cDNA in Keap1 mutant cells significantly enhances the sensitivity to cisplatin." (PMID 35945195, 2022). "Inactivation of Kelch-like ECH-associated protein-1 (Keap1) strongly induces NF-E2-related factor 2 (Nrf2), and acquires malignancy in several types of cancer." (PMID 35945195, 2022).